INS (insulin)
Diseases named in the same sentence as INS in open-access papers (continued):
Sharing a sentence is not in itself a finding about the gene and the disease.
Hyperinsulinemia (continued). "Women on hormonal replacement therapy and who received medicine to control hyperinsulinemia under insulin-resistant conditions were excluded, but other intervening pharmacologic factors could make variations in primary measured variables." (PMID 31752829, 2019). "On the other hand, the increased circulating irisin may represent an “irisin resistance” state, similar to the insulin and leptin resistance that results in hyperinsulinemia and hyperleptinemia observed in obese individuals." (PMID 31015797, 2019). "In addition, it has been reported that adult rats treated with MSG displayed hyperinsulinemia, pointing to an impairment of insulin sensitivity." (PMID 30738429, 2019). "Hyperinsulinemia and high level of IGF-1 are associated with CRC progression, thus, insulin based treatment among diabetic patients might impose the risk of CRC occurrence." (PMID 31831021, 2019). "Further, chronic hyperinsulinemia is thought to lead to lower insulin levels in the brain, which could explain why treating with insulin has been shown to cause memory improvements." (PMID 31616284, 2019). "In order to investigate further regulation of circulating lymphocytes and monocytes, we investigated responses of these immune cell populations to insulin action; namely, we studied these populations during short-term hyperinsulinemia induced by hyperinsulinemic-euglycemic clamp." (PMID 30983877, 2019). "Consequently, the use of insulin-sensitizing agents able to mitigate hyperinsulinism, such as metformin, for the prevention and treatment of cancer was also suggested." (PMID 31533348, 2019). "Congenital hyperinsulinism is a rarely reported feature of the syndrome with the genetic mechanism for the dysregulated insulin secretion being unknown." (PMID 32832699, 2019). "Tyrosine depleted Tyros 2 treated rodents also showed increased insulin excursion relative to the complete mixed meal formula, a finding that is possibly relevant to the observation that hyperinsulinism is a known comorbidity of patients with Tyrosinemia type 1 treated with reduced TYR/PHE diets." (PMID 30876866, 2019). "We hypothesise that the pathophysiology of hyperinsulinism in VWM may involve dysregulation of transcription of genes related to insulin secretion." (PMID 32071834, 2019). "Another factor contributing to this effect might be severe hyperinsulinemia in diabetic subjects, as high levels of insulin were shown to reduce systemic ANGPTL3 by decreasing its liver expression." (PMID 29695708, 2018). "Hyperinsulinemia insulin-resistant states could also contribute to cardiac remodeling and ventricular dysfunction through the growth-promoting activity of insulin." (PMID 30089498, 2018). "Therefore, we consider that the enhanced adipocyte insulin signaling by Ipra, probably via improving hyperinsulinemia, results in increased lipid-storage capacity in adipocytes." (PMID 30382157, 2018). "Recently, one interesting study has compared the effects of rapamycin treatment on different diabetic mouse models and unexpectedly demonstrated that rapamycin improves insulin sensitivity and reduces hyperinsulinemia better in mice with lower pancreatic insulin content." (PMID 30011848, 2018). "Furthermore, data on the metabolic consequences of equine insulin dysregulation, other than hyperinsulinemia, are still limited." (PMID 29716602, 2018). "Although our data support the hyperinsulinemia-causes-IR hypothesis, short-term PRKD2 inhibition or deficiency may have beneficial effect via enhancing glucose-stimulated insulin secretion." (PMID 29789568, 2018). "These long-term deleterious effects could result from GLP-1-induced insulin secretion in β cells and hyperinsulinemia, thereby leading to decreased insulin sensitivity and/or augmented priming effects on β cells." (PMID 29556215, 2018).
Hyperinsulinemia (continued). "Hyperinsulinemia is often linked with sugar-rich diet feeding; however, in present study, serum insulin levels did not alter upon glucose feeding which concurs with earlier reports." (PMID 30386595, 2018). "Thus, elevated BMD in T2DM, at least in the early phase, hallmarked by increased insulin level, then later when the pancreases cannot be able to secrete enough insulin to overcome the increased insulin resistance that results in periods of hyperinsulinemia." (PMID 29755605, 2018). "It was also noted that insulin, though not estrogen, appears to influence desaturase activity, as demonstrated by the increased desaturase function associated with hyperinsulinemia in obese women." (PMID 30103441, 2018). "Moreover, despite peripheral hyperinsulinemia, insulin levels in the portal veins are low in CLD patients with portal systemic shunting." (PMID 29614124, 2018). "Finally, insulin and Aβ are both substrates of insulin-degrading enzyme and it has been suggested that hyperinsulinemia inhibits the degradation of Aβ by competitively blocking insulin-degrading enzyme." (PMID 30355995, 2018). "On the other hand, the increased glucose levels observed in the HP group, might be indicative of hyperinsulinemia, and insulin can also upregulate the activity and expression of SCD43." (PMID 29426919, 2018). "In addition, because of lower circulating levels of insulin in DKO and PS10-treated DIO mice, insulin sensitivity is restored in both animal groups as a result of tempered hyperinsulinemia." (PMID 29656110, 2018). "However, it has been shown that feeding regimens which increase insulin (hyperinsulinemia) stimulate follicular growth and increase follicular recruitment in heifers and mares." (PMID 30774266, 2018). "Equine insulin dysregulation reflected by hyperinsulinemia is a key symptom." (PMID 29716602, 2018). "The high-fat diet also increased serum insulin levels (hyperinsulinemia) in those mice." (PMID 29677191, 2018). "According to several studies, high glucose level of a gestational diabetic mother may induce the release of insulin from the fetal pancreas, leading to fetal hyperinsulinemia." (PMID 30539027, 2018). "Taken together, these results jointly indicate that a deficiency in PRKD2 leads to hyperinsulinemia by regulating insulin secretion rather than altering insulin signaling." (PMID 29789568, 2018). "Furthermore, insulin signaling in heart tissue is compromised owing to a hyperinsulinemia-driven reduced insulin receptor number." (PMID 30314283, 2018). "Thus, both monkeys with extreme hyperinsulinemia exhibited markedly augmented glucose-induced insulin secretion and severe IR." (PMID 29789568, 2018). "Serum C peptide (C-P) was decreased due to Tg effects, and insulin levels were increased due to the effects of the HFHSD in the Tg HFHSD group, indicating that damaged insulin secretion and insulin resistance hyperinsulinemia existed simultaneously in these animals." (PMID 29682407, 2018). "We aimed to assess adipose tissue and skeletal muscle sirtuin 1 expression in relation to insulin sensitivity, the expression of proinflammatory and metabolic genes, and to study the regulation of sirtuin 1 expression by hyperinsulinemia and circulating free fatty acids elevation." (PMID 29417372, 2018). "Similarly, HFD caused a significant increase of fasting insulin levels, and the supplementation of bovine α-LAH strongly suppressed the hyperinsulinemia." (PMID 29473848, 2018). "Functional studies indicate that the GDM-related miRNA-340 responds to insulin and glucose in cultured lymphocytes and could therefore be of importance in hyperinsulinemia-induced changes in gene expression." (PMID 29358694, 2018). "Also plasma lipid levels (TC, TG, and LDL-C), fasting blood sugar levels, hyperinsulinemia (insulin levels) and high insulin resistant (high HOMA-IR values) were significantly higher in subjects who had significantly low plasma Cr level (p ≤ 0.001)." (PMID 29975702, 2018).
Hyperinsulinemia (continued). "The ability to reduce insulin secretion, and therefore hyperinsulinemia, through the use of eGLP-1R antagonism is an exciting outcome of this study which may represent a promising, and novel, approach to managing equine insulin dysregulation." (PMID 29404215, 2018). "In addition, it would have been more elegant to compare GU and EGP between fasting state and hyperinsulinemia to measure insulin sensitivity." (PMID 29535167, 2018). "Under chronic hyperinsulinemia, such as when insulin clearance is impaired, the pulsatility of insulin secretion is diminished, resulting in blunted acute insulin signaling, hepatic insulin resistance and limited counter-regulation of lipogenesis." (PMID 30314283, 2018). "In this situation, impaired glucose uptake in insulin-sensitive tissues and hepatic glucose production lead to an increase in insulin secretion in order to maintain normal glucose levels, that is, compensatory hyperinsulinemia." (PMID 29971102, 2018). "Moreover, metformin use in T2DM improves the sensitivity of peripheral tissues to insulin, which results in a reduction of circulating insulin levels, thus decreasing the effect of hyperinsulinemia in reducing the excretion of uric acid." (PMID 30349765, 2018). "In addition,hyperinsulinemia was observed with insulin sensitivity damage, since the glucose AUCwas higher in group HF than group C." (PMID 29069204, 2017). "Nevertheless, they stayed normoglycemic under steady-state conditions due to the hyperinsulinemia they were exhibiting accompanied by an enhanced glucose stimulated insulin secretion (GSIS) which both resulted in normal glucose uptake from the skeletal muscle and the WAT." (PMID 28546545, 2017). "Since insulin has anti-inflammatory actions, it is tempting to speculate that one of the functions of hyperinsulinemia is to suppress low-grade systemic inflammation." (PMID 28824543, 2017). "Furthermore, the mice were also extremely insulin resistant, as indicated by their hyperinsulinemia and low glucose decay during the insulin tolerance test." (PMID 28708105, 2017). "Furthermore, calreticulin, a C1QR, showed upregulated gene expression in the heavier co-twins and correlated positively with hyperinsulinemia and negatively with the genes involved in the insulin signaling route." (PMID 28559893, 2017). "Metformin, which acts as an insulin-sensitizing agent, decreases IGF-1 by indirectly down-regulating insulin and insulin-binding proteins to reverse hyperinsulinemia, which may be a mechanism for metformin’s anticancer effects." (PMID 28126011, 2017). "The transient increase of insulin caused transitions towards inflammatory or TGFβ producing cell types under basal insulin level, while, as expected, under hyperinsulinemia the transient activation of insulin did not cause any further transitions." (PMID 28651594, 2017). "Prolonged hyperinsulinemia and/or fatty pancreas may in turn lead to the dysfunction of pancreatic β-cells, resulting in impaired insulin secretion." (PMID 29165385, 2017). "Further examination of the 13 normoglycemic subjects with low plasma or serum water T2 values yielded the following observations:A.Three of the 13 subjects had overt compensatory hyperinsulinemia, with fasting insulin above 12.2 μIU/mL and insulin C-peptide in the top tertile." (PMID 29258604, 2017). "Accordingly, we hypothesize that hyperinsulinemia is secondary to the hyperandrogenism in some degree, and administration of T may improve the differentiation efficiency of insulin-producing cells from hiPSCs." (PMID 28594910, 2017). "Moreover, 45% patients presented hyperinsulinemia at baseline with an average level of insulin of 19.17 mU/L." (PMID 28744472, 2017). "Although the mechanism is not very clear, the hypothesis is the internal environment disorder with insulin resistant and hyperinsulinemia, which promote thyroid cells proliferation as well as inhibit apoptosis." (PMID 28107199, 2017).
Hyperinsulinemia (continued). "Equine metabolic syndrome (EMS) is an endocrine disease that is characterized by a multiplate pathophysiological condition including hyperinsulinemia and/or resistance to insulin (IR), past and/or chronic laminitis, hyperlipidemia as well as local and systemic inflammation." (PMID 29292726, 2017). "On the other hand, 12-month-old mice still showed hyperinsulinemia but normal mitochondrial function in skeletal muscle, therefore other factors in addition to insulin have to be involved in the increased mitochondrial performance observed in 6-month-old IR-IRS1dh animals." (PMID 28556799, 2017). "Thus, hyperinsulinemia may predispose the progeny of an overnutritioned breast-feeding mother for future long-lived metabolic disease through hypothalamic IR signalling, whereas the inability to sense the abnormally high levels of insulin acting on POMC neurons during lactation prevents it." (PMID 28469281, 2017). "Chronic stress, such as that of chronic disease or emotional stress may have similar effects on systemic insulin responses, resulting in a reduction in whole body insulin sensitivity manifesting as hyperinsulinemia." (PMID 29280741, 2017). "Hyperinsulinemia concomitant with maintained insulin sensitivity in adipose relative to muscle tissue is observed during weight regain after weight loss, physical inactivity, or in metabolically healthy obese subjects relative to insulin resistant subjects and during earlier stages of pregnancy." (PMID 28406437, 2017). "In addition, AMPK activity can be inhibited by insulin and glucose in several tissues, as it would be the case with the hyperinsulinemia characteristic of this experimental animal model." (PMID 28753963, 2017). "Alternatively, maternal hyperinsulinemia might lead to insulin transition to the fetus, resulting in fetal hyperinsulinemia." (PMID 29191195, 2017). "The evidence suggests that high-glycemic load diets can contribute to acne by inducing hyperinsulinemia, while low-glycemic load diets may prevent hyperinsulinemia by lowering postprandial insulin." (PMID 28513546, 2017). "CL-316243, a β3-adrenergic receptor agonist that sensitizes to insulin action, reduced hyperinsulinemia and phosphorylation of insulin and IGF-1 receptors and attenuated mammary tumor progression, supporting a role for hyperinsulinemia in T2DM associated tumor progression." (PMID 28060743, 2017). "Furthermore, in a GPx1 overexpressing male mice model that is characterized by IR, hyperglycemia, hyperinsulinemia, increased fat deposits and plasma leptin, and diminished insulin sensitivity." (PMID 28981461, 2017). "The resulting increase of hepatic glucose release could promote hyperinsulinemia and insulin insensitivity." (PMID 28926951, 2017). "Therefore, overexpression of betatrophin induced by insulin in PHMs unlikely contributed to extracellular/circulating concentrations of the protein as seen in vivo hyperinsulinemia." (PMID 29228555, 2017). "Though AD patients were found with peripheral hyperinsulinemia, AD patients have reduced levels of insulin in the cerebrospinal fluid (CSF), indicating that insulin signaling activities may be below the normal threshold in the brain." (PMID 28282917, 2017). "Taken together, these studies suggest that, in insulin-resistant patients, the concomitance of increased TSH levels, deregulation of the IGF axis, and hyperinsulinemia, may represent significant risk factors for TC." (PMID 29184536, 2017). "The insulin signaling pathways may be involved in inflammation leading to hyperinsulinemia, which further stimulates secretion of androgen by ovaries and disturbs follicular development." (PMID 26799617, 2016). "In addition to reproductive features of the syndrome, previous studies have demonstrated an association between PCOS and derangements in glucose metabolism, particularly impaired insulin action and compensatory hyperinsulinemia." (PMID 27505055, 2016).
Hyperinsulinemia (continued). "Hyperinsulinemia, even at physiologic levels, may actually stimulate a further worsening of insulin sensitivity in diabetes, thereby promoting a vicious cycle that places an unrelenting demand on pancreatic β-cell function." (PMID 27929385, 2016). "Therefore, we consider that ipragliflozin treatment enhanced adipocyte insulin signaling via improving hyperinsulinemia, thereby resulting in increased lipid-storage capacity in adipocytes." (PMID 26977813, 2016). "For example, Some intervention studies reported exercise may reduce plasma insulin levels and increase insulin sensitivity, thus attenuating hyperinsulinemia." (PMID 27437765, 2016). "The unbalanced insulin signalling through compensatory hyperinsulinemia also characterizes T2DM." (PMID 27562101, 2016). "Insulin-stimulated phosphorylation of IRS-1ser307 may occur due to feedback inhibition of the insulin signaling cascade reported during conditions of hyperinsulinemia." (PMID 27695421, 2016). "In the heart, leptin or insulin may be considered either metabolic or growth factors for the heart and hyperinsulinemia and hyperleptinemia are documented in SL rodents at several stages of development." (PMID 27465434, 2016). "Chronic hyperinsulinemia may have consequences on the OSNs properties through the insulin transduction pathway." (PMID 27659313, 2016). "In humans it is discussed that both the degree of insulin sensitivity and the level of hyperinsulinemia may affect blood pressure through separate pathways." (PMID 27766986, 2016). "Apart from direct effects of insulin on cancer cells, it is possible that hyperinsulinemia could promote carcinogenesis indirectly through the effects of insulin effects on IGF126." (PMID 26983499, 2016). "Thus, in addition to the impact of systemic hyperinsulinemia, the interpretation of global insulin signaling defects must consider the actions of insulin at the hypothalamus as well as disruption to the regulation of early follicle development by IGF1." (PMID 27375552, 2016). "Iron may decrease insulin extraction and metabolism in the liver, which could lead to hyperinsulinemia." (PMID 27231921, 2016). "As a consequence, independent of laboratory and assay-specific reference ranges or cut-off values, a general harmonization of equine insulin analyses is urgently required to allow accurate and safe diagnosis of hyperinsulinemia as one of the leading symptoms in horses suffering from EMS." (PMID 27613127, 2016). "Actually administration of atypical antipsychotics may result in increase of food intake, stimulating insulin release, post prandial hyperinsulinemia, and weight gain." (PMID 27610173, 2016). "Our results imply that stimulatory effects of fatty acids on insulin secretion at fasting glucose concentrations may contribute to hyperinsulinemia in subjects with elevated levels of FFAs." (PMID 27582778, 2016). "Thus, Map4k4 mediates hyperinsulinemia in chronic obesity by promoting islet hypertrophy and insulin secretion from pancreatic β cells." (PMID 27226575, 2016). "This insulin-resistant state promotes an increase in pancreatic β cell mass and enhanced insulin secretion to normalize glucose levels, which results in hyperinsulinemia." (PMID 27226575, 2016). "The glucose lowering effect in an insulin-independent manner of SGLT-2 inhibitors prevents hyperinsulinemia, which may also contribute to anti-atherogenesis." (PMID 26668677, 2016). "Chronically, however, prolonged hyperinsulinemia in normoglycemic conditions may decrease insulin sensitivity." (PMID 26927166, 2016). "Interestingly, the rats fed the C diet had the highest (p < 0.05) level of serum insulin, which was high enough to be considered hyperinsulinemia, whereas the rest of the groups had normal insulin concentrations." (PMID 27657118, 2016). "Hyperinsulinemia may also be a potential contributor to cancer as the metabolic effect of insulin may promote the Warburg effect." (PMID 26939025, 2016).